IL7 (interleukin 7)
Diseases named in the same sentence as IL7 in open-access papers (continued):
Sharing a sentence is not in itself a finding about the gene and the disease.
adenovirus infection (1 paper, 2020). "However, a separate study has reported that Dkk3-carrying adenovirus infection of normal human fibroblasts induced interleukin-7 production, triggered by ER stress proteins (ASK1, p38, IRE1α and IRF-1)." (PMID 33425757, 2020).
age (1 paper, 2025). A temporal measurement of the time period elapsed since an identifiable point in the life cycle of an organism. "For example, interleukin-7 (IL-7), an age-associated cytokine, shows elevated expression in cardiac, pulmonary, and vascular tissues of elderly individuals and upregulates ACE2 expression in vascular endothelial cells through NF-κB-dependent mechanisms." (PMID 40370452, 2025).
alcohol (1 paper, 2019). "Sil increased the levels of RBP4 and reduced the levels of IL-7, YKL 40, and PAI-1 in the liver (p < 0.05), but only reduced the levels of YKL 40 and PAI-1 in the serum of mice with alcohol-induced acute liver injury (p < 0.05)." (PMID 31396303, 2019).
angiokeratoma (1 paper, 2020). A vascular lesion in the papillary dermis resulting from ectasia of pre-existing vessels. "Of note, FGF2, IL-7 and VEGFA explained solely a small variance fraction of phenotype, sudation disorder, and angiokeratoma, respectively." (PMID 32370284, 2020).
aplastic anemia (1 paper, 2024). Anemia resulting from bone marrow failure (aplastic or hypoplastic bone marrow). "In a recent report, IL-7, GM-CSF, and G-CSF were administered together with L-AmB and posaconazole to successfully cure a lymphopenic patient with aplastic anemia and mucormycosis." (PMID 38921374, 2024).
ATTRv amyloidosis (1 paper, 2022). "On the contrary, serum levels of IL-7 were lower in our ATTRv amyloidosis patients." (PMID 36552168, 2022). "In conclusion, the results of this pilot study suggest that ATTRv amyloidosis is characterized by a modification of serum levels of IFN-alpha, IFN-gamma, and IL-7." (PMID 36552168, 2022).
autoimmune encephalitis (1 paper, 2018). Inflammation of the brain secondary to an immune response triggered by the body itself. "Similarly, in a previous report, another anti-IL-7Rα mAb prevented in vitro and ex vivo IL-7-induced pSTAT5 in primates but did not protect from brain inflammation in an experimental autoimmune encephalitis (EAE) marmoset model." (PMID 30367166, 2018).
B-cell lymphopenia (1 paper, 2018). "B-cell lymphopenia is common among HD patients and is due to an increased apoptosis mediated by a decreased Bcl-2 expression and a resistance to IL-7 and B-cell-activating factor of the TNF family, both necessary for the differentiation and survival of B-cells." (PMID 29963040, 2018).
biphasic mesothelioma (1 paper, 2022). "Among MPM patients, biphasic mesothelioma (BM) seemed to express low level of IL‐7 compared to sarcomatoid (SM) and epithelioid mesothelioma (EM)." (PMID 36054746, 2022).
bone metastasis (1 paper, 2006). Transfer of a neoplasm from its primary site to bones. "We demonstrated the presence of high serum IL-7 levels in patients with bone metastasis, suggesting the use of serum IL-7 level as a clinical marker of disease progression and of bone involvement." (PMID 17205128, 2006). "We did not appreciate any significant differences in IL-7 expression in cancer patients with or without bone metastasis." (PMID 17205128, 2006).
Candida infections (1 paper, 2025). "Candida infections and injection site reactions were more frequent with IL-7 inhibitors, whereas infusion reactions and serious infections were more commonly associated with TNF-α inhibitors." (PMID 41235248, 2025).
cardiac hypertrophy (1 paper, 2024). "The most significantly affected signaling pathways were EIF-2, IL-2, integrin, NGF, VEGF, estrogen receptor, IL-7, FLT3, FGF, oxytocin, cardiac hypertrophy, role of NFAT in cardiac hypertrophy, and neutrophil extracellular trap pathways." (PMID 38047311, 2024).
cataract (1 paper, 2020). Partial or complete opacity of the crystalline lens of one or both eyes that decreases visual acuity and eventually results in blindness. "The level of IL-12p40, MIP-1d, IL-7, IL-6R, BLC, TNF-a, IL-5 were elevated in the SG samples compared to the samples of the cataract patients." (PMID 32117217, 2020).
cholesteatoma (1 paper, 2023). A pathologic process characterized by the proliferation of keratinizing squamous epithelium resulting in the accumulation of keratin and cells in the middle ear and/or mastoid. "It is due to lytic enzymes such as collagenase and inflammatory mediators such as TNF alpha, IL-1,1L-6, IL-7, IFN beta, epidermal growth factor TGF-alpha, and matrix metalloproteinase, released by cholesteatoma matrix and granulation tissue." (PMID 37664290, 2023).
chordoma (1 paper, 2024). Chordomas are rare malignant tumors arising from embryonic remnants of the notochord in axial skeleton. "The high percentage of CD8+ T cells also promoted the killing ability of B7–H3 CAR-T/IL-7 cells against chordoma cells." (PMID 39093440, 2024). "Fourteen chordoma samples were analyzed by single-cell RNA sequencing, and B7–H3 and IL-7 were identified as potential targets and potentiators, respectively." (PMID 39093440, 2024). "We, therefore, compared the cytotoxicity of two CAR-T-cell structures on chordoma cells and found that B7–H3 CAR-T/IL-7 had better cytotoxicity against chordoma cells." (PMID 39093440, 2024). "B7–H3-targeted chimeric antigen receptor T (CAR-T) cells and B7–H3 CAR-T cells expressing IL-7 were synthesized and their anti-tumor activity evaluated in vitro, including in primary chordoma organoid models." (PMID 39093440, 2024). "We thus designed CAR-T cells targeting B7–H3 and, after finding that IL-7 is also highly expressed in chordoma samples, coupled sequences to secrete IL-7 from B7–H3 CAR-T cells, thereby enhancing the anti-tumor and sustained killing ability of CAR-T cells." (PMID 39093440, 2024). "B7–H3 CAR-T/IL-7 cells showed enhanced cytotoxicity and a sustained killing effect against chordoma cells." (PMID 39093440, 2024). "Furthermore, B7–H3 CAR-T/IL-7 cells showed better killing ability against patient-derived chordoma cells and sustained anti-tumor capacity." (PMID 39093440, 2024). "In cytotoxicity assays against chordoma cells performed at different time points, B7–H3 CAR-T/IL-7 cells remained lethal to chordoma cells on day 17, and the addition of IL-7 mAb to the B7–H3 CAR-T/IL-7 and chordoma cell co-culture system attenuated the sustained killing of tumor cells." (PMID 39093440, 2024). "Notably, B7–H3 CAR-T/IL-7 cells exhibited superior sustained cytotoxicity toward chordoma organoids." (PMID 39093440, 2024). "Moreover, B7–H3 CAR-T cells effectively bound IL-7 within the system, mitigating immunosuppression and enhancing the cytotoxicity of CAR-T cells against chordoma cells." (PMID 39093440, 2024). "The incorporation of IL-7 molecules into the B7–H3 CAR structure augmented CAR-T-cell function and improved CAR-T-cell efficacy, thus providing a novel dual therapeutic strategy for chordoma treatment." (PMID 39093440, 2024). "Taking the pathological characteristics of the chordoma TME into account, we designed a CAR-T-cell preparation, B7–H3 CAR-T/IL-7, that not only recognizes the chordoma-specific antigen B7–H3 but also enhances the anti-tumor capacity of CAR-T cells by secreting IL-7." (PMID 39093440, 2024).
chronic heart failure (1 paper, 2011). "It is worth noting that our study, for the first time, has associated IL-5, IL-7, IL-9, and IFN-γ plasma levels with chronic heart failure." (PMID 21418620, 2011). "Further studies are needed to assess whether the modification of IL-5, IL-7, IL-9 and IFN-γ plasma levels has a null, a protective, or a pathogenetic role in chronic heart failure and may constitute a potential target for therapeutic intervention." (PMID 21418620, 2011). "However, what was noteworthy, and described here for the first time, was the increase of IL-9, and decrease of IL-5, IL-7 and IFN-γ plasma levels in patients with chronic heart failure." (PMID 21418620, 2011).
chronic hepatitis B (1 paper, 2017). "When comparing HCC and non-HCC cases, profiles of HCC and non-HCC chronic hepatitis B patients were rather different with resistin being the most predictive cytokine followed by IL-7 and IL-8 (AUC = 0.744) and less so for chronic hepatitis C patients (AUC = 0.635)." (PMID 28928388, 2017).
colorectal adenoma (1 paper, 2015). An adenoma that arises from the colon or rectum. "Therefore, the aim of our study was to determine if inflammation was increased in study participants with colorectal adenomas relative to control participants using a novel methodology based on the stability of interleukin-7 (IL-7) in serum samples." (PMID 25884547, 2015).
cutaneous melanoma (1 paper, 2022). A primary melanoma arising from atypical melanocytes in the skin. "In summary, insufficient IL-7 secretion might contribute to CD8+ T cell exhaustion and CD127 dysregulation in patients with primary cutaneous melanoma." (PMID 35850640, 2022).
cutaneous T-cell lymphoma (1 paper, 2021). "Indeed, stimulation with IL-7 promoted the proliferation of cutaneous T-cell lymphoma (CTCL) cells, and also Sézary lymphoma cells were sensitive to IL-7." (PMID 34066732, 2021).
cyst (1 paper, 2025). A sac-like closed membranous structure that may be empty or contain fluid or amorphous material. "Future studies, investigating IL-7 at the site of cyst development, may be useful to address this issue." (PMID 40407653, 2025).
delirium (1 paper, 2025). A disorder characterized by confusion; inattentiveness; disorientation; illusions; hallucinations; agitation; and in some instances autonomic nervous system overactivity. "The study indicates that the levels of INS, BCL2L1, and IL‐7 in CSF may be linked to the risk of delirium, with INS playing a pivotal role." (PMID 40922636, 2025). "In the PPI network analysis, INS, BCL2L1, and IL‐7 were identified as central nodes, indicating their potential significant role in the pathophysiology of delirium." (PMID 40922636, 2025). "Network analysis revealed several central nodes, including INS, BCL2L1, and IL‐7, which exhibited high connectivity, suggesting that these CSF proteins may play a central role in the pathophysiology of delirium." (PMID 40922636, 2025). "Larger nodes like INS, IL7, and BCL2L1 suggest central roles in the delirium pathway." (PMID 40922636, 2025). "Our preliminary findings suggest a potential negative correlation between IL‐7 levels and delirium, but further research is needed to validate these results." (PMID 40922636, 2025).
dilated cardiomyopathy (1 paper, 2011). Cardiomyopathy which is characterized by dilation and contractile dysfunction of the left and right ventricles. "Interestingly, local production of IL-7 has been associated with the maintenance and predominance of CD8+ T cells, which cause tissue damage in human chronic Chagas' disease cardiomyopathy, an inflammatory-dilated cardiomyopathy." (PMID 21418620, 2011).
dyslipidaemia (1 paper, 2018). "Here we observed a strong correlation between free cholesterol within VLDL-2 and both CCL-17 and IL-7 highlighting a potential interaction between inflammation and dyslipidaemia." (PMID 30451923, 2018).
dysplasia (1 paper, 2024). A usually neoplastic transformation of the cell, associated with altered architectural tissue patterns. "In laboratory experiments, isolated cells expressing CCL20 and CCR4, stimulated by IL-5 and IL-7, demonstrated an increased ability of CD8+ T cells to penetrate dysplastic cells, thereby improving therapeutic efficiency in fighting dysplasia." (PMID 39273632, 2024).
endotoxemia (1 paper, 2024). "IL7 mediates T-cells’ transmigration from circulation to the gastrointestinal tract, which typically occurs in response to dietary endotoxemia." (PMID 39457699, 2024).
eosinophilic pneumonia (1 paper, 2020). An inflammatory lung disorder characterized by an increased number of eosinophils in the lungs. "The main mechanism of acute eosinophilic pneumonia has been elucidated to be due to pro-inflammatory cytokines such as IL-5, IL-6, IL-7, and tumor necrosis factor." (PMID 32366239, 2020).
epithelioid mesothelioma (1 paper, 2022). "The prognostic value of IL‐7 was also conserved when only patients with epithelioid mesothelioma, the most common histological type of MPM, were analyzed." (PMID 36054746, 2022).
falciparum malaria (1 paper, 2019). "Results presented here suggest that variation in IL7 is associated with altered erythropoietic responses in children with uncomplicated vs. severe falciparum malaria." (PMID 31420016, 2019). "Taken together, variation in IL7 is associated with erythropoietic responses in children with falciparum malaria, a central physiological feature contributing to development of SMA." (PMID 31420016, 2019).
fibrosarcoma (1 paper, 2025). A malignant mesenchymal fibroblastic neoplasm affecting the soft tissue and bone. "Interestingly, in a transplanted fibrosarcoma model derived from 3MC-induced MC51-9 fibrosarcoma cells, intratumoral Ad.IL-7/B7.1 was efficacious, leading to 87.5% (7/8) tumor-free long-term survivors." (PMID 40957993, 2025).
Flavivirus Infections (1 paper, 2020). Infections with viruses of the genus FLAVIVIRUS, family FLAVIVIRIDAE. "Harnessing cytokine signaling pathways has been proposed to treat other sexually-transmitted virus infections, including IL-7 in HIV, IFNα in HCV, and JAK/STAT pathways in other flavivirus infections." (PMID 33378361, 2020).
focal epilepsy (1 paper, 2024). A seizure caused by a localized disorder. "Specifically, focal epilepsy onset may induce increases in cytokines such as IL-7, IL-1Ra, IL-10, TNF-α, IFN-γ, and IL-1β, whereas inconsistent cytokine levels, including IL-5 and IL-1ra, may influence variations in focal epilepsy risk." (PMID 39259090, 2024).
Follicular Cyst (1 paper, 2023). Cyst due to the occlusion of the duct of a follicle or small gland. "FGF7 regulated the PPAR signaling pathway (FABP5 and SCD) and the MAPK signaling pathway (FGF1, FGFR2, IL1A, TGFB1, and CSF1) and pathways in cancer (IL7, CD44, SMAD2, and MMP2) may be involved in the formation of follicular cysts." (PMID 38274662, 2023).
gallstones (1 paper, 2021). Solid crystalline precipitates in the biliary tract, usually formed in the gallbladder, resulting in the condition of cholelithiasis. "The correlations between IL-4 and IL-6, as well as between IL-6 and IL-7, suggest that the initiated inflammatory response to gallstone induced injury is being actively intensified and sustained through cytokines modulated intercellular signalling pathway." (PMID 34449702, 2021).
gastric polyps (1 paper, 2024). "Through bidirectional investigation approach, it could be inferred that certain biomarkers are more likely to be found later in the course of the illness, like bNGF, FGFBasic, GCSF, GROa, IL-13, IL-5, IL-7, MCSF, SCGFb in gastric polyps, and CTACK, MIF in colonic polyps." (PMID 39439893, 2024).
gastritis (1 paper, 2019). Inflammation of the stomach. "Like in bowel inflammation, the upregulation of IL-7 mRNA has been reported in association with gastritis in Helicobacter pylori-positive patients." (PMID 31185636, 2019).
genital wart (1 paper, 2025). "The increased expression of GZMB, IFNG, IL-12B, and IL-8 and the decreased expression of NFATC4 and IL-7 in genital wart samples were highlighted." (PMID 40142865, 2025).
gestational diabetes (1 paper, 2020). Carbohydrate intolerance first diagnosed during pregnancy. "Nevertheless, the higher expression of IL-7 in placentas of women in the GDM group supports the thesis of a proinflammatory environment in gestational diabetes." (PMID 33126577, 2020). "IL-7 expression could be identified in the EVT of placentas with gestational diabetes, as well as in those of the control group." (PMID 33126577, 2020).
granular corneal dystrophy type II (1 paper, 2024). Type II granular corneal dystrophy (GCDII) is a rare form of stromal corneal dystrophy characterized by irregular-shaped well-demarcated granular deposits in the superficial central corneal stroma, and progressive visual impairment. "Kim SY reported that IL-7 plays a critical role in corneal fibroblasts in granular corneal dystrophy type 2 by reducing the expression of TGF-β and TGFBI through regulation of the RNNKI/RANK signaling cascade and by regulating the expression of MT-MMP." (PMID 38455059, 2024).
Granuloma (1 paper, 2020). A compact, organized collection of mature mononuclear phagocytes, which may be but is not necessarily accompanied by accessory features such as necrosis. "The granuloma model demonstrated a Th1 cytokine profile with increased secretion of IL-2R, IL-7, IL-12, IFN-γ, and TNF-α." (PMID 32350353, 2020). "We also found that α-MSH exerts anti-inflammatory effects on this granuloma model with a clear reduction of IL-7, IL-7R, and IFN-γ." (PMID 32350353, 2020). "A significant increase in IL-7, IL-7R, and IFN-γ protein expression was found in developed granulomas comparing to microparticle unchallenged PBMCs." (PMID 32350353, 2020). "We observed that RNA expression of IL-7, IL17A, IL6, MARCO, IFN-γ, and IL-8 was significantly decreased in granulomas treated with α-MSH compared to the controls." (PMID 32350353, 2020). "IL-7, IL-7R, and IFN-γ protein expression was significantly reduced in developed granulomas after exposure to α-MSH compared with saline treated granulomas." (PMID 32350353, 2020). "However, it has been suggested that cytokines including IL-2, IL-7, IL-8, IL-12, IFN-γ, TNF-α, and GM-CSF have an important role in initiation and continuation of granuloma formation." (PMID 32350353, 2020).
hantavirus infection (1 paper, 2018). "Three of them were directly linked to immune pathways (Toll‐like receptor cascades, JAK–STAT pathway and regulation, IL‐7 signaling) and one of them (VEGF signaling pathway) is known to be activated during hantavirus infection (Hepojoki, Vaheri, & Strandin, 2014)." (PMID 30519443, 2018).
helminth infection (1 paper, 2018). "IL-2, IL-7 and IL-15 could possibly serve as lymphoid growth factors and could underlie novel strategies for immune recovery and the optimization of immune therapies in helminth infections." (PMID 29795573, 2018). "The role of CD4+ and CD8+ T cell subset distribution and the association between memory T cell subsets and the common γc cytokines (IL-2, IL-4, IL-7, IL-9 and IL-15) in helminth infections has not been explored well." (PMID 29795573, 2018). "However, the effects of helminth infection on common γc cytokine—IL-2, IL-4, IL-7, IL-9 and IL-15- levels have not been explored in Ss infection." (PMID 29795573, 2018).
hip fracture (1 paper, 2022). Traumatic or pathological injury to the hip in which the continuity of either the femoral head, femoral neck, intertrochanteric or subtrochanteric regions is broken. "Unsurprisingly, our study also observed significantly increased levels the Th1 (combination of IL-2, IFN-γ and IL-12) and T cell growth and activation factors (a combination of IL-4, IL-7, IL-9, IL-12, IL-15, GM-CSF) in the delirious hip fracture patients compared to the non-delirious group." (PMID 35641947, 2022).